CRP (C-reactive protein)
Diseases named in the same sentence as CRP in open-access papers (continued):
Sharing a sentence is not in itself a finding about the gene and the disease.
depression (continued). "In the linear analysis, serum magnesium levels were inversely associated with depression scores in the groups of CRP levels ≥ 5 mg/L (β = −0.50, 95% CI = −0.97, −0.03; p = 0.039) and of <5 mg/L (β = −0.17, 95% CI = −0.33, −0.00; p = 0.045)." (PMID 37049401, 2023). "Growing evidence indicate that elevated concentrations of inflammatory markers are associated with depression and anxiety, including C-reactive protein (CRP), interleukin 6 (IL-6), and other inflammatory markers." (PMID 37344456, 2023). "This definition was also applicable to evidence that increased CRP levels are associated with depression and elevated central nervous system biomarkers." (PMID 37049401, 2023). "Growing evidence has also confirmed the association between chronic inflammation and depression, manifested with increased C-reactive protein levels and proinflammatory cytokines, such as IL-1 β, IL-6, and TNF-α." (PMID 38138916, 2023). "A meta-analysis examining the relationship between depression and inflammation in children and adolescents found that depression was significantly associated with elevated levels of CRP and IL-6." (PMID 37840796, 2023). "In 493 patients that had undergone laparoscopic gastric banding surgery, CRP was positively correlated with Beck Depression Inventory (BDI), a score that assesses the risk for depression." (PMID 37529617, 2023). "Serum magnesium levels were inversely associated with depression scores more prominently among people with higher CRP levels, with a threshold at 5 mg/L (≥5 vs. <5) showing a greater difference than at 3 mg/L (≥3 vs. <3)." (PMID 37049401, 2023). "Baseline C-reactive protein did mediate this association, but the amount of variance accounted in the relation between VRFs and depression was relatively small." (PMID 37881584, 2023). "This suggests that inflammatory activity itself has an impact on psychological well-being, especially since several studies have associated higher blood CRP levels with more severe depression symptoms and poorer response to antidepressant treatment." (PMID 37324155, 2023). "Circulating Nucb2 has been associated with panic disorder, reported depression, depression associated with subclinical hypothyroidism, and carcinogenesis and correlated with inflammatory markers such as IL-6 and C-reactive protein as well as corticosterone." (PMID 37386441, 2023). "Genotyping in patients with heart failure and comorbid depression revealed that genetic variants implicated in anxious behaviour (NPSR1) as well as inflammation (C-reactive protein (CRP), interleukin 6 (IL-6)) modify the risk of progression and mortality." (PMID 36959471, 2023). "High consumption of processed and red meats was associated with elevated levels of low-grade inflammation (C-reactive protein) and pro-inflammatory adipokine (leptin) as well as subsequent brain atrophy which is positively correlated with depression." (PMID 37432385, 2023). "Systematic reviews have also found positive associations between depression and other blood inflammatory markers, such as C-reactive protein and interleukin-1." (PMID 37764129, 2023). "One such biomarker that is implicated in a multitude of afflictions like depression and Brugada syndrome is the C-reactive protein (CRP)." (PMID 37754956, 2023). "In our study, lead SNPs in loci associated with depression and CRP had concordant direction of effects." (PMID 35560157, 2022). "Subjects who displayed a pattern of increasing CRP levels from childhood to early adulthood had a higher risk of moderate/severe depression at 18 years, compared to those who had persistently low CRP levels." (PMID 35163538, 2022). "We applied novel statistical tools for polygenic architectures to investigate if there are common genes for depression, coronary artery disease and cardiovascular risk factors (body mass index, blood pressure, lipids, type 2 diabetes and c-reactive protein)." (PMID 35560157, 2022).
depression (continued). "Later studies have linked CRP and IL-6 to specific symptoms of depression and identified a potential causal link between IL-6 and depression." (PMID 35618889, 2022). "It has also been reported that high CRP levels are associated with psychological disorders such as depression and bipolar mood disorders." (PMID 36232200, 2022). "For instance, increased C-reactive protein (CRP) is associated with a dysfunctional corticostriatal reward circuit—a key component of treatment-resistant depression." (PMID 36291336, 2022). "Conversely, rs1205 was found to be nominally associated with both an increased risk of depression and lower circulating CRP levels in women." (PMID 35163538, 2022). "Given the large number of tests conducted, we calculated FDR corrected p values for the associations between ACEs and the CRP/depression trajectories." (PMID 35241782, 2022). "Age-adjusted multivariable regression analysis of the association of C-reactive protein levels with body mass index, headache frequency per month, and the severity of anxiety and depression." (PMID 36313504, 2022). "In this study, we present comprehensive Mendelian randomization analyses testing the direction and potential causality of association between smoking, CRP, and depression." (PMID 36057695, 2022). "Previous prospective studies generally suggest that depressive symptoms or episodes of depression are associated with CRP levels longitudinally, although there has been some variability in these results." (PMID 35617264, 2022). "A cross-sectional study recruiting 43,896 adults examined the association between CRP levels and depression in terms of executive functioning." (PMID 35163538, 2022). "While studies generally agree that cytokines such as IL-6 and TNF-α are correlated with depression, the role of CRP (a cytokine that generally exhibits robust correlations with depression) specifically in HIV-associated depression is a major area of debate." (PMID 35618889, 2022). "Previous studies on high-sensitivity C reactive protein (hs-CRP) have produced mixed results regarding the association between depression and hs-CRP." (PMID 35504874, 2022). "Positive associations between CRP and depression have been established in both clinical and community samples, but effect sizes are attenuated after controlling for confounding variables." (PMID 35821205, 2022). "For example, depression is associated with the release of C-reactive protein (CRP) and cytokines such as IL-1, IL-2, IL-6, IFN-γ, and IL-1β." (PMID 35562885, 2022). "Children with elevated levels of IL-6 and C-reactive protein at 9 years of age are at a higher risk of depression onset by 18 years of age." (PMID 36619667, 2022). "The similarity in findings between the present and previous studies suggests that the present study appropriately evaluated the association between CRP, anxiety, depression, BMI, and migraine." (PMID 36313504, 2022). "At the same time, it was found that a high level of CRP was associated more with impaired cognitive parameters (low psychomotor speed) than with the main symptoms of depression." (PMID 35163141, 2022). "The study reported that depression and higher CRP levels were both associated with worse executive functioning, even after covariates adjustment." (PMID 35163538, 2022). "Associations between CRP levels and depression remain significant even after controlling for some clinical and psychosocial factors, and elevations in CRP levels predict decreased functional connectivity in key brain regions." (PMID 35618889, 2022). "Depression is also associated with elevated levels of inflammatory factors such as C-reactive protein (CRP), tumor necrosis factor-alpha (TNF-α), and interleukin 6 (IL-6)." (PMID 35360021, 2022). "The association of C-reactive protein (CRP), another inflammatory biomarker, with depression has also been investigated." (PMID 36368945, 2022).
depression (continued). "Inflammation in the periphery (typically measured by pro-inflammatory cytokines and acute phase reactants like C-Reactive Protein [CRP]) is implicated in several psychiatric illnesses in the general population including depression, anxiety, and PTSD." (PMID 35836664, 2022). "More specifically, cortisol was no longer associated with depression, whereas larger associations were observed between CRP and depression and between ACEs and anxiety during the pandemic." (PMID 36198766, 2022). "Overall from this review, it is evident that elevated CRP levels in the mTBI patient population are positively associated with depression and PTSD." (PMID 35053845, 2022). "Longitudinal studies have also demonstrated that higher levels of serum IL-6 and CRP in childhood are associated with increased risk of psychotic disorders and depression in early-adulthood, consistent with MR studies." (PMID 36277463, 2022). "An observational study investigated the association between CRP levels and depression also considering shared genetic and environmental factors." (PMID 35163538, 2022). "Increased levels of IL-6 and CRP are not only associated with major depression, but also with RA, and in the latter illness, IL-6 is associated with increased CDAI, DAS28, and bone erosions." (PMID 35330475, 2022). "A longitudinal study aimed at examining the association between depression and hs-CRP levels, found a positive association between BDI scores and serum hs-CRP levels only in women." (PMID 35163538, 2022). "The associations of ACEs with the CRP and depression trajectories mirrored those found across specific early-life periods (Model 1)." (PMID 35241782, 2022). "For example, depression and frailty were positively associated with C-reactive protein, interleukin-1, and interleukin-6." (PMID 36360934, 2022). "In the general population, an elevated C-reactive protein (CRP) level is linked to a higher risk of developing depression." (PMID 36761172, 2022). "In a multivariate analysis study on RA severity, elevated serum IL-6 and CRP levels were associated with depression severity." (PMID 35330475, 2022). "Hair cortisol was related to an increased risk of depression (OR = 1.15[95%CI:1.04,1.26]), and CRP was associated with greater loneliness scores (b = 0.16[95%CI:0.03,0.30])." (PMID 36198766, 2022). "A large population-based cross-sectional study recruited 5447 Korean people aged > 20 years, from the Korean National Health and Nutrition Examination Survey (KNHANES VII-1), to assess the association between hs-CRP and depression." (PMID 35163538, 2022). "Sleep deficiency results in the release of inflammatory markers, such as C-reactive protein and interleukin, which are associated with depression." (PMID 35599763, 2022). "Variants associated with increased risk for depression also increased the risk of coronary artery disease, some of the lipids and c-reactive protein levels, while there was a mixed pattern of direction for the other risk factors." (PMID 35560157, 2022). "Regarding depression, elevated CRP levels were associated with depressive symptoms in studies from Western Europe and North America but not in Asia and the Middle East." (PMID 36313504, 2022). "Our results suggest potentially causal bi-directional associations of smoking with depression and CRP levels." (PMID 36057695, 2022). "In contrast, another recent systematic review which included 22 studies on children and adolescents, reported both cross-sectional and prospective associations between CRP, IL-6, and clinical depression." (PMID 35360574, 2022). "Conversely, while ART normalises the levels of some inflammatory cytokines in people living with HIV, concentrations of other cytokines such as IL-6 and CRP (which are strongly linked to depression) remain elevated." (PMID 35618889, 2022). "On the other hand, other studies displayed opposite results with a positive association between CRP levels and depression only among women." (PMID 35163538, 2022).
depression (continued). "ACEs were consistently associated with all psychological distress outcomes, hair cortisol was associated with an increased risk of depression, and high CRP levels were related to greater loneliness scores." (PMID 36198766, 2022). "Mounting observational evidence suggests psychiatric disorders including schizophrenia, major depressive disorder and bipolar disorder are associated with elevated CRP levels." (PMID 36075890, 2022). "Objective measures, such as swollen joint counts and inflammatory markers of disease activity, like the CRP, have been variably associated with baseline depression in different studies." (PMID 36422176, 2022). "The influence of inflammation on kynurenine pathway activity is important in the context of ECT, as depression has consistently been shown to be associated with chronic low-grade inflammation (review and meta-analysis:, recent original paper on CRP:)." (PMID 36422569, 2022). "↑WS depression had a higher polygenic risk for BMI [OR = 1.20 (1.15–1.26), p = 2.37 × 10−14] and C-reactive protein [OR = 1.11 (1.06–1.17), p = 8.86 × 10−06] v. non-↑WS depression and ↓WS depression." (PMID 32624019, 2022). "More recently, using the MR approach Kappelmann and colleagues have reported that inflammatory markers like CRP and IL-6 are associated with specific symptoms of depression, such as suicidality." (PMID 36057695, 2022). "Six genomic loci were associated jointly with depression and coronary artery disease, 69 with blood pressure, 49 with lipids, 9 with type 2 diabetes and 8 with c-reactive protein at conjFDR < 0.05." (PMID 35560157, 2022). "For instance, a recent cumulative meta-analysis reported that interleukin-6 (IL-6), IL-1β and C-reactive protein (CRP) are associated with depression." (PMID 35496273, 2022). "A later cross-sectional study confirmed a positive association between high sensitive serum CRP (hs-CRP) and depression-score, controlling for anthropometric and lifestyle factors." (PMID 35292108, 2022). "The mutually adjusted associations of the ACEs dimensions with the CRP and depression trajectories were almost identical to those found in the analysis testing each dimension individually (Model 5)." (PMID 35241782, 2022). "CRP and IL-6 were positively associated with anhedonia, and cortisol levels were related to both anhedonia and depression." (PMID 36090246, 2022). "Higher level of systemic inflammatory markers such as CRP in the childhood was associated with an increased risk of developing depression and psychosis in young adulthood." (PMID 35418067, 2022). "The present work aims to review the literature on the association between C-Reactive Protein (CRP) and depression." (PMID 35163538, 2022). "Other studies looking at depression using whole-brain analysis showed that CRP and inflammatory cytokine levels were associated with decreased connectivity within the reward-related brain regions." (PMID 36422176, 2022). "Pro-inflammatory diets, such as the Western diet, can raise the levels of pro-inflammatory biomarkers (e.g., C-reactive protein (CRP), interleukin 6 (IL-6)), which can increase the risk for the development of depression." (PMID 35565951, 2022). "Biomarkers of peripheral inflammation, such as inflammatory cytokines and C-reactive protein (CRP), are useful indicators of current and future health and (like depression) have been linked with poor sleep." (PMID 35617264, 2022). "Higher levels of Il-6, CRP, and dysregulation of the cortisol response are linked with cardiovascular disease and depression." (PMID 35279110, 2022). "A cross-sectional population-based study evaluated the association between depression and CRP in 6126 adults, assessed with the Center for Epidemiologic Studies Depression (CESD) scale." (PMID 35163538, 2022). "Both CRP and IL-1β have been implicated in the pathophysiology of psychological conditions, particularly major depressive disorders." (PMID 36612568, 2022).
depression (continued). "The effect of BMI PRS and CRP PRS on the risk of ↑WS depression was similar when taking healthy controls as comparator group, while it was in the opposite direction or absent, respectively, when we compared ↓WS depression v. healthy controls." (PMID 32624019, 2022). "Significant proportions of the influence of depression on clinical risks were explained by CRP (4.8% on IHD hospitalizations), GLR (11% on all-cause mortality), and WBC (24% on IHD/CeVD hospitalizations)." (PMID 36311535, 2022). "None of the examined risk factors of CVD, but a positive history of depression was consistently identified as a significant predictor of persistently increased CRP levels in both fully adjusted regression models." (PMID 35566447, 2022). "We explored the relative contribution of anxiety/depression, smoking, body mass index (BMI) and inflammation (C-reactive protein, CRP) to the association between childhood maltreatment and CVD in men and women aged 40–69 years in the UK." (PMID 34041541, 2022). "This concentration threshold (>3 mg/L) has also been associated with increased risk for future episodes of depression, and on average, CRP has been reported to be elevated in depressed versus healthy populations." (PMID 35821205, 2022). "According to our previous review, IL-6, IFN-α, and TNF-α and CRP were associated with depression and anxiety." (PMID 35053845, 2022). "Multinomial logistic regression analysis, controlling for covariates, showed that depression scores were positively associated with serum hs-CRP levels (p < 0.001)." (PMID 35163538, 2022). "Anxiety/depression, smoking, BMI and CRP mediated 26–40% of the associations between childhood maltreatment and CVD in men and 30–90% of the associations in women." (PMID 34041541, 2022). "First, other potential contributing factors, such as depression, cognition, social interactions, obstetric complications, or factors associated with CRP, such as viral infections, smoking, or body mass index, were left unexplored." (PMID 35151465, 2022). "The IVW method supported evidence for associations of genetically-predicted lifetime smoking index with risk of depression (ORSmk–Dep = 2.01, 95% CI : 1.71–2.37, p < 0.001), and CRP levels (ORSmk–CRP = 1.40, 95% CI: 1.27 − 1.55, p < 0.001)." (PMID 36057695, 2022). "Together, anxiety/depression, smoking, BMI and inflammation (indexed by CRP) mediated 26–90% of the association between childhood maltreatment and CVD, and the contribution of these mediators differed by type of maltreatment and sex." (PMID 34041541, 2022). "Overall, the present systematic review reported that most studies here retrieved, found a positive association between elevated CRP levels and depression." (PMID 35163538, 2022). "Several inflammatory markers, namely interleukin-1β (IL-1β), IL-6, and C-reactive protein (CRP), are associated with depression." (PMID 36188478, 2022). "We examined the predictive value of a history of depression in 183 patients with acute MI at 3-month follow-up for the persistence of initially increased CRP, which is known to be a risk factor for CVD." (PMID 35566447, 2022). "Nonetheless, knowledge on the shift in CRP-related CVD-risk categories related to lifetime depression can be of clinical use to identify patients at need for tailored anti-inflammatory interventions in the aftermath of MI." (PMID 35566447, 2022). "Reports consistently suggest that increased IL-6, TNF-α, and CRP levels are risk factors for mood and depressive disorders." (PMID 35558424, 2022). "In this study, serum CRP and IL-6 were positively associated with anhedonia, whereas cortisol levels were related to both severities of depression and anhedonia in MDD." (PMID 36090246, 2022). "We investigated the magnitude of associations between C-reactive protein (CRP) measures, lifetime history of bipolar disorder or major depression, and cognitive function (reaction time and visuospatial memory) in 84,268 UK Biobank participants." (PMID 33517931, 2021).